AQP3 (aquaporin 3 (Gill blood group))
Diseases named in the same sentence as AQP3 in open-access papers (continued):
Sharing a sentence is not in itself a finding about the gene and the disease.
influenza (2 papers, 2021 to 2022). An acute viral infection of the respiratory tract, occurring in isolated cases, in epidemics, or in pandemics; it is caused by serologically different strains of viruses (influenzaviruses) designated A, B, and C, has a 3-day incubation period, and usually lasts for 3 to 10 days. "Thus, further investigation is warranted to determine whether AQP3 mediates the adaptation of γδ T cells to hypoxic conditions in influenza-infected lungs." (PMID 33772013, 2021).
intervertebral disc degeneration (2 papers, 2022). "Moreover, CCL5, AQP3 and SDC4 may improve the chemotaxis of stem cell migration for self-healing of damaged disc tissue, increase water uptake by nucleus accumbens cells, and inhibit the inflammatory response, thus delaying the process of intervertebral disc degeneration." (PMID 36506585, 2022).
kidney failure (2 papers, 2016 to 2022). An acute or chronic condition that is characterized by the inability of the kidneys to adequately filter the blood. "AQP3 and UT-B (SLC14A1) gene expression was evaluated using RT-qPCR analysis in 76 HD patients and 35 participants with no kidney failure." (PMID 36038817, 2022).
kidney transplant (2 papers, 2020). A surgical procedure in which one or both kidneys from a donor are implanted into a recipient. "We next investigated the involvement of AQP3 in oxidative stress in the chronic liver injury model." (PMID 33168815, 2020). "Thus, our study elucidated mechanistic insights on the AQP3 SNP and transposed them to an in vivo setting by investigating graft rejection and genotype dependent CMV infection rates in kidney transplant recipients." (PMID 32521638, 2020).
Leukaemia (2 papers, 2010 to 2015). "Recent data from our laboratory demonstrated the capacity of specific AQP isoforms (AQP8 and AQP3) to channel NADPH oxidase- (Nox-) produced hydrogen peroxide across plasma membrane in leukaemia cells, affecting downstream redox signaling pathways linked to leukaemia cell proliferation." (PMID 26346093, 2015).
liver disease (2 papers, 2013 to 2021). "AQP3 was expressed in hepatocytes and Kupffer cells which are involved in pathogenesis of liver diseases." (PMID 34360801, 2021).
meningioma (2 papers, 2016 to 2023). A generally slow growing tumor attached to the dura mater. "In agreement, TRAF7-deficient MEFs also had an increased expression of several investigated TRAF7 meningioma signature genes, including IL1RL1, KRT16, KRT6A, and AQP3." (PMID 36937440, 2023). "Furthermore, human glia-derived brain tumors (gliomas, glioblastomas, meningiomas and schwannomas) do not express AQP3 arguing for a potentially neuron specific expression." (PMID 27487831, 2016).
metastasis (2 papers, 2012 to 2017). The spread or migration of cancer cells from one part of the body (where they first appeared) to another. "We previously demonstrated that AQP3 is overexpressed in GC tissues and that its expression is associated with increased histological classification, lymph node metastasis and lymphovascular invasion." (PMID 28968998, 2017).
nephrogenic diabetes insipidus (2 papers, 2023 to 2024). Nephrogenic diabetes insipidus (NDI) is characterized by polyuria with polydipsia, recurrent bouts of fever, constipation, and acute hypernatremic dehydration after birth that may cause neurological sequelae. "Downregulation of AQP2 and AQP3 is also common in several types of nephrogenic diabetes insipidus (NDI)." (PMID 38791455, 2024). "The impact of TAM on AQP3 regulation was studied in rats subjected to 7 days of unilateral ureteral obstruction (UUO), with the rats fed a lithium-containing diet to induce nephrogenic diabetes insipidus (NDI), as well as in human precision-cut kidney slices (PCKS)." (PMID 37190049, 2023).
oral squamous cell carcinoma (2 papers, 2020 to 2024). "Matsuo and Kauano demonstrated that AQP3 expression is an independent prognostic factor for lymphatic metastasis of oral squamous cell carcinoma." (PMID 32075009, 2020).
pancreatitis (2 papers, 2018 to 2025). Inflammation of the pancreas. "This suggests that AQP3 and TRIB2 may also play a role in regulating the immune microenvironment of pancreatitis." (PMID 40076525, 2025). "In contrast to AQP1, AQP3 is not expressed in the mouse pancreas and this isoform is either involved in tumor progression than pancreatitis." (PMID 30050452, 2018).
periodontitis (2 papers, 2016 to 2023). An acute or chronic inflammatory process that affects the tissues that surround and support the teeth. "It is recommended that future researchers also evaluate salivary AQP-3 protein concentrations in patients with chronic periodontitis utilizing the recent classification of periodontitis." (PMID 37027451, 2023).
Polyuria (2 papers, 2024 to 2025). An increased rate of urine production. "Our findings demonstrate that UA reduces the expression of AQP2, AQP3 and AQP4 in an NFκB-dependent manner, which contributes to the polyuria phenotype in the subjects with HUA." (PMID 40271210, 2025). "Collectively, our findings demonstrate that UA reduces the expression of AQP2, AQP3 and AQP4 in an NFκB-dependent manner, which contributes to the polyuria phenotype in subjects with HUA." (PMID 40271210, 2025). "In conclusion, we report that HUA can damage urine concentration capacity leading to a polyuria phenotype via down-regulating AQP2, AQP3 and AQP4 expression in the kidney." (PMID 40271210, 2025). "We revealed that patients and mice with HUA had a polyuria phenotype and found that the expression of aquaporin 2 (AQP2), AQP3 and AQP4 were significantly reduced in the kidneys of mice with HUA." (PMID 40271210, 2025).
preeclampsia (2 papers, 2018 to 2022). Preeclampsia is a hypertensive disorder of pregnancy that is characterized by new-onset hypertension with proteinuria presenting after 20 weeks of gestation, and depending on mild or severe forms may initially present with severe headache, visual disturbances, and hyperreflexia. "Cell line studies showed that the inhibition of AQP3 reduces cell migration in trophoblast cells and expression of AQP3 was found to be significantly reduced in preeclampsia." (PMID 36550527, 2022). "One possibility is that AQP3 decreases as an adaptive response of the trophoblast to reduce the apoptotic events observed in preeclampsia." (PMID 30425647, 2018). "In this context, we assumed that the increase in trophoblast apoptosis observed in preeclampsia might correlate with an increase in AQP3, but we found a reduced expression of this protein in these placentas." (PMID 30425647, 2018). "Given that preeclampsia is a syndrome of early placentation, we cannot discard that the abnormal expression of AQP3 and AQP9 observed at the end of gestation may be a consequence of a failure in the differentiation of the trophoblast stem cell." (PMID 30425647, 2018). "Along with this idea, we expected that an altered AQP3 may be one of the key factors in the development of preeclampsia." (PMID 30425647, 2018). "Considering that preeclampsia is related to an abnormal placentation and an altered placental expression of AQP3 and AQP9 was found after the onset of the maternal syndrome, we assumed that these proteins may participate in the early stages of placental development." (PMID 30425647, 2018). "Consequently, the role of AQP3 in the apoptosis of the VT in preeclampsia remains unclear." (PMID 30425647, 2018). "We believe that in preeclampsia complicated by IUGR, the aberrant expression of AQP3 may be present already in the undifferentiated trophoblast stem cell affecting both VT and EVT pathways." (PMID 30425647, 2018).
primary effusion lymphoma (2 papers, 2018 to 2022). A large B-cell lymphoma located in the body cavities, characterized by pleural, peritoneal, and pericardial fluid lymphomatous effusions and that is always associated with human herpes virus-8 (HHV-8). "AQP3 has been reported as Kaposi’s sarcoma-associated herpes virus (KSHV) associated non-Hodgkin’s lymphoma (NHL) or primary effusion lymphoma (PEL) defining gene." (PMID 30555637, 2018). "An involvement of AQPs has been also reported in primary effusion lymphoma (PEL), an aggressive AIDS-linked KSHV-associated non-Hodgkin’s lymphoma, which is characterized by the increased production of AQP3." (PMID 36077720, 2022).
renal fibrosis (2 papers, 2022 to 2023). A final common manifestation of a wide variety of chronic kidney diseases characterized by glomerulosclerosis and tubulointerstitial fibrosis. "Lastly, the impact of TAM on AQP3 regulation was examined in an ex vivo model of human renal fibrosis, namely human precision-cut kidney slices (PCKS)." (PMID 37190049, 2023). "Our results demonstrated that TAM treatment could rescue AQP3 expression in different models of renal fibrosis (e.g., rats subjected to UUO and TGF-β-exposed human PCKS) as well as in rats with LiCl-induced NDI." (PMID 37190049, 2023). "In alloxan-induced DN rats, rutin ameliorated renal fibrosis and metabolic acidosis via reducing the metabolic acidosis-related genes aquaporin 2 (AQP2), aquaporin 3(AQP3), and arginine vasopressin receptor 2 (V2R)." (PMID 35408760, 2022).
Sjögren’s syndrome (2 papers, 2023 to 2025). "Most studies on AQP-3 in humans were performed using biopsy specimens of minor salivary glands for the diagnosis of Sjögren’s syndrome." (PMID 37027451, 2023).
thyroid cancer (2 papers, 2012 to 2022). "In thyroid cancer cell lines, using RT-PCR and western blotting, AQP3 mRNA and protein were only identified in the TT cell line (human medullary carcinoma cell line) and AQP4 in the other cell lines." (PMID 22808259, 2012). "Nevertheless, in thyroid cancer, AQP3 mRNA and protein were only identified in medullary thyroid cancer derived from C cells, which might be interpreted as stimulation by hormones secreted by C cells such as calcitonin." (PMID 35972604, 2022). "We examined mRNA expression profiles of AQP3 and AQP4 in eight thyroid carcinoma cell lines using RT-PCR." (PMID 22808259, 2012). "Thus, we examined the expression of AQP3 and AQP4 in normal, hyperplastic and neoplastic thyroid tissues in conjunction with human thyroid cancer cell lines." (PMID 22808259, 2012).
urothelial bladder carcinomas (2 papers, 2012 to 2020). "The present study is the first to investigate a larger patient cohort of pT1 urothelial bladder carcinomas for AQP3 protein expression." (PMID 23043286, 2012).
urothelial carcinoma (2 papers, 2012). A malignant neoplasm derived from the transitional epithelium of the urinary tract (urinary bladder, ureter, urethra, or renal pelvis). "Although the present study did not investigate the underlying molecular mechanisms of AQP expression in urothelial carcinoma, our findings suggest that AQP3 may be an independent predictor of tumour progression from stage pT1 towards stage pT2 tumours." (PMID 23043286, 2012). "Moreover, investigations into the molecular mechanisms of AQP3 expression in urothelial carcinoma are required to understand its role in the pathogenesis of UBC." (PMID 23043286, 2012).
acute kidney injury (1 paper, 2024). Sudden and sustained deterioration of the kidney function characterized by decreased glomerular filtration rate, increased serum creatinine or oliguria. "AQP3, on the other hand, modulates inflammation through the Toll-like receptor 4 (TLR4) pathway, while AQP1 plays a role in immune responses by activating the PI3K pathway, promoting macrophage polarization, and protecting against lipopolysaccharide (LPS)-induced acute kidney injury (AKI)." (PMID 39544938, 2024).
acute promyelocytic leukemia (1 paper, 2024). An aggressive form of acute myeloid leukemia (AML), characterized by arrest of leukocyte differentiation at the promyelocyte stage, due to a specific chromosomal translocation t(15;17) in myeloid cells. "Cell proliferation was analyzed in the acute promyelocytic leukemia (APL) cell line NB4 which showed expression of all three aquaglyceroporins AQP3, AQP7, and AQP9." (PMID 38319972, 2024).
adenoma (1 paper, 2026). A neoplasm arising from the epithelium. "WJW increased/normalized the expression of key epithelial transport proteins involved in Na+/Cl- absorption and water handling, including sodium/hydrogen exchanger 3 (NHE3), epithelial sodium channel (ENaC), downregulated in adenoma (DRA), aquaporin-3 (AQP3), and aquaporin-8 (AQP8)." (PMID 41675980, 2026).
Af (1 paper, 2021). "Here, we demonstrated a novel mechanism by which partially hydrolysed whey formula and its hydrolysate can reduce TEWL, modulate barrier-related gene expression notably AQP3 gene, and thus possibly improve skin barrier function in an Af model." (PMID 34578990, 2021).
apocrine carcinoma (1 paper, 2021). "Positive AQP3 staining was seen in sweat gland tumors including hidradenoma, eccrine poroma, and apocrine carcinoma." (PMID 34745849, 2021).
benign skin tumors (1 paper, 2021). "Among the benign skin tumors, positive AQP3 staining was seen in all 7 hidradenomas (all diffuse), 6/7 eccrine poromas (all diffuse), all 16 sebaceomas (4/16 focal, 4/16 intermediate, and 8/16 diffuse), and all 10 sebaceous adenomas (all diffuse)." (PMID 34745849, 2021).
bladder diseases (1 paper, 2023). "The present study was performed as a first step towards exploring the possible involvement of AQPs in As‐ and PPD‐induced bladder diseases and we demonstrated that the expressions of AQP3, 4, 7, 9, and 11 were differentially regulated by arsenate and PPD." (PMID 37719549, 2023).
brain trauma (1 paper, 2024). "The analysis of the literature demonstrated that the most significant markers among the AQPs are as follows: for the brain, AQP4, which is very important in brain trauma and hypoxic damage; AQP3 in the skin lesions caused by various mechanisms; and AQP5 in the diagnosis of drowning." (PMID 38473914, 2024). "The analysis of the literature demonstrated that the most significant markers among the AQPs are AQP4 for the brain, which is very important in brain trauma and hypoxic damage; AQP3 in the skin lesions caused by various mechanisms; and AQP5 in the diagnosis of drowning in lung and kidney samples." (PMID 38473914, 2024).
celiac disease (1 paper, 2021). An autoimmune genetic disorder with an unknown pattern of inheritance that primarily affects the digestive tract. "However, in other study comparing normal subjects vs. celiac disease patients, AQP3 was abundantly expressed but the protein localized at enterocyte apical membranes." (PMID 33465153, 2021).
Cerebral ischemia (1 paper, 2023). Restriction of arterial blood supply to the brain associated with insufficient oxygenation to support the metabolic requirements of the tissue. "All of these indicate that AE can reduce the expression of aquaporins (AQP3, AQP4, and AQP5) in PSD rats’ brain tissue and alleviate the damage status of depressed rats after cerebral ischemia." (PMID 36982280, 2023).
cholelithiasis (1 paper, 2023). The presence of crystallized deposits forming in the gallbladder or biliary tree, primarily composed of cholesterol, bilirubin, and bile. "To investigate whether AQP3 was associated with LPS-induced inflammatory injury of gallbladder mucosal epithelial cells, we examined the injury of gallbladder mucosal epithelial cells in mice with cholelithiasis." (PMID 37641009, 2023). "This study reports a mechanistic insight into AQP3 regulating gallstone formation in cholelithiasis based on high-throughput sequencing." (PMID 37641009, 2023). "RT-qPCR and Western blot experiments showed that AQP3 was significantly down-regulated in the gallbladder tissues of mice with cholelithiasis." (PMID 37641009, 2023). "It should be noted that aquaporin 3 (AQP3) was screened as the important differentially expressed gene (DEG) in cholelithiasis." (PMID 37641009, 2023). "Our study aims to investigate the possible molecular mechanism of AQP3 in regulating cholelithiasis, involved with regulating the AMPK/SIRT1 signaling pathway, in the hope of finding novel directions for repressing and treating cholelithiasis." (PMID 37641009, 2023). "Our study only used the high cholesterol method, and further research using various modeling methods and clinical studies is needed to understand the crucial role of AQP3 in cholelithiasis." (PMID 37641009, 2023). "Bioinformatics analysis revealed that AQP3 was significantly down-regulated in mice with cholelithiasis." (PMID 37641009, 2023). "Inflammatory injury of gallbladder mucosal epithelial cells affects the development of cholelithiasis, and aquaporin 3 (AQP3) is an important regulator of inflammatory response." (PMID 37641009, 2023). "Firstly, although we observed the corresponding molecular changes and inflammatory damage in cholelithiasis model mice that overexpressed AQP3, further exploration using knockout gene mice is necessary." (PMID 37641009, 2023). "Based on high-throughput sequencing, this study explored the possible molecular mechanism by which AQP3 affected gallstone formation in cholelithiasis." (PMID 37641009, 2023). "AQP3 was poorly expressed in the mucosal tissues of mice with cholelithiasis." (PMID 37641009, 2023). "Our study found that AQP3 was significantly downregulated in mice with cholelithiasis and that AQP3 might have an important role in LPS-induced gallbladder mucosal injury." (PMID 37641009, 2023). "To verify whether the changes of AQP3 in the gallbladder tissues of mice with cholelithiasis were consistent with the sequencing results, we examined the expression of AQP3 in the gallbladder tissues of normal control mice and mice with cholelithiasis." (PMID 37641009, 2023). "Our in vivo animal studies revealed that AQP3 is a negative regulator of inflammatory injury of the mucosal epithelium of the gallbladder in mice with cholelithiasis and is a potential target for treating cholelithiasis." (PMID 37641009, 2023). "Notably, there is a scarcity of reports regarding the role of AQP3 in cholelithiasis." (PMID 37641009, 2023). "However, the role and specific mechanism of AQP3 in cholelithiasis remains unclear." (PMID 37641009, 2023).
chronic myeloid leukemia (1 paper, 2025). "Recently, a genome-wide CRISPR/Cas9 screen in the human chronic myeloid leukemia cell line K562 identified ABCC1, SLC30A1, and AQP3 as important regulators of arsenic toxicity." (PMID 39578074, 2025).